IL10 (interleukin 10)
Diseases named in the same sentence as IL10 in open-access papers (continued):
Sharing a sentence is not in itself a finding about the gene and the disease.
diabetes (continued). "Present study revealed that diabetes increased TNFα as a pro-inflammatory cytokine and reduced IL-10 as an anti-inflammatory cytokine in BALF." (PMID 38233819, 2024). "We examined the effects and mechanisms of action of IL-10-treated adipose-derived stromal cells on diabetes-induced insulin resistance and liver gluconeogenesis." (PMID 39125659, 2024). "Diabetes reduced the IL-10, IL-11, and Nrf2 levels (P<0.001 to P<0.01) and increased the levels of TNF-α and NF-κB compared to the Col group (P<0.001)." (PMID 38164478, 2024). "Next, we determined the effect of Brazil nut and metformin on diabetes-instigated cardiac inflammation by measuring the cardiac concentrations of NFkB and IL-10 in the rats." (PMID 39239455, 2024). "We examined levels of key factors that are associated with proinflammation and significantly altered in diabetes (IL1β, IL6 and IL10) and that are associated with angiogenesis (VEGF-A) in M1 macrophages." (PMID 38270651, 2024). "The results of this study demonstrated that induction of diabetes significantly decreased pulmonary levels of IL-10 and IL-11 in the Dia group compared to the Col group (P<0.01)." (PMID 38164478, 2024). "As an example, oral Lactococcus secreted IL10 to limit islet infiltration by immune cells and prevent and halt the progression of diabetes." (PMID 38543910, 2024). "A plethora of evidence suggest the pathogenic role of proinflammatory cytokine IL17 and protective role of anti-inflammatory cytokine IL10 in diabetes and hypertension." (PMID 38835661, 2024). "Given the stable high expression of IL-10 in both controls and both types of diabetes, it appears that immune tolerance is maintained in HBCs." (PMID 38590527, 2024). "High glucose levels reduce AMPK activity which has a key role in inflammation, hence type 2 diabetes mellitus-induced inflammation interferes with IL-10 signaling." (PMID 38164478, 2024). "Tr1 cells, likely arising from memory and total CD4 T-cells, controlled effector T-cells via IL10 signaling to limit the development of diabetes." (PMID 38543910, 2024). "We examined the effects and mechanism of IL-10-treated adipose stromal cells on diabetes-induced gluconeogenesis and insulin resistance." (PMID 39125659, 2024). "An experimental study demonstrated that moderate and regular exercise training reduces CRP, IL-6, TNF-α and increases adiponectin levels and IL-10.In general, exercise has anti-inflammatory effects especially in diabetes." (PMID 38233819, 2024). "IL-10 improves beta cell function, inhibits insulitis progression, and prevents diabetes in animal models." (PMID 39125659, 2024). "In summary, we demonstrate the potential protective effects of IL-10-modulated adipose-derived stromal cells in decreasing diabetes-induced DPP4 activity, insulin resistance, and liver gluconeogenesis." (PMID 39125659, 2024). "HGF has anti-inflammatory properties; it can increase IL-10 levels and reduce IL-1β levels in pancreatitis or diabetes." (PMID 38533089, 2024). "IL-10 has been well demonstrated to have anti-inflammatory and anti-nociceptive effects in animal models of neuropathic pain, peripheral diabetic pain, bone cancer pain, and inflammatory pain." (PMID 37639183, 2024). "Injection of IL-10-treated SVFs into the adipose tissue decreased diabetes-induced gluconeogenesis gene expression, DPP4 activity, and insulin resistance by enhancing Treg cells in diabetic mice." (PMID 39125659, 2024). "Similar to what has been observed in patients with diabetes, high glucose levels can impair the IL-10 signaling protein—signal transducer and activator of transcription 3 (STAT3)—and lead to IL-10 hyporesponsiveness." (PMID 39062154, 2024). "New evidence has also been shed on the idea that IL-10 plays a role in the interrelationship between OA and diabetes." (PMID 37255905, 2023).
diabetes (continued). "Regarding IL-10, in a study with mice presenting severe hepatic steatosis and defective insulin signal transduction plus diabetes, animals were treated with two daily doses of an IL-10 inhibitor for 5 days." (PMID 37593740, 2023). "Prolonged enhanced concentrations of the pro‐inflammatory cytokines IL‐1β and TNFα in blood, and reduced anti‐inflammatory IL‐10 in sputum, have been observed in patients with TB and diabetes comorbidity, in accordance with our results." (PMID 37649224, 2023). "The logistic regression equation included five variables: diabetes, decompensated liver cirrhosis, long-term use of immunosuppressive agents, decreased serum albumin level, and elevated plasma cytokine IL-10 level." (PMID 38115055, 2023). "Comorbidities, such as hypertension and diabetes, can also affect the production of pro-inflammatory cytokines including IL-2R, IL-10 and TNF-α." (PMID 37969879, 2023). "Several studies have shown that administration of exogenous IL-10 can prevent the development of insulitis or diabetes in NOD mice." (PMID 37296126, 2023). "On the other hand, when adjusting for age, sex, hypertension, diabetes mellitus, ALT, AST, GGT, creatinine, and uric acid (Model 2), only IL-6, IL-10, TNF, and IP-10 levels remained significantly associated with AF." (PMID 36834735, 2023). "Our data demonstrated that the serum proinflammatory cytokines IL-1β, TNF-α, IL-2, IFN-γ, and IL-4 and the anti-inflammatory cytokine IL-10 were dysregulated in diabetes and improved by OI intervention." (PMID 36918798, 2023). "This supports that the absence of CX3CR1 recruits bone marrow derived immune populations into the retina, as well as reduced IL-10 expression, which is upregulated during clearance of diabetes-induced apoptotic cells." (PMID 36869375, 2023). "In the mouse model, the levels of IL-6 and IL-10 were found to be significantly decreased in the latent tuberculosis with diabetes group in comparison to the latent tuberculosis only group." (PMID 36776550, 2022). "IL-10 is considered an anti-inflammatory cytokine with lower circulating levels in patients with type 2 diabetes mellitus." (PMID 35330193, 2022). "Consistent with our previous results, the level of IL-6 and IL-10 in patients with diabetes was significantly elevated than those in HC individuals." (PMID 35242878, 2022). "Less IL-10 production by regulatory T and B cells is found in children with diabetes, which cytokine is found to play a protective role against T1D development." (PMID 35903316, 2022). "In contrast, IL-10, an anti-inflammatory cytokine produced by Treg cells, inhibits the progression of diabetes in an animal model." (PMID 36327331, 2022). "Significantly less TGFβ1 was detected in GFP+ microglia from mice with IL-10 depletion, suggesting that IL-10 depletion suppressed the M2c differentiation of microglia in diabetes." (PMID 35935990, 2022). "The incidence of diabetes development was accelerated by blockade of IL-10 compared to isotype control treatment." (PMID 35444659, 2022). "The experimental results suggested that interleukin-10 is expected to become a detection index of myocardial infarction in diabetes." (PMID 36712879, 2022). "Significantly less Caspase 3 (Casp3) was detected in NeuN+ neuronal cells from mice with IL-10 depletion, suggesting that IL-10 depletion reduced apoptosis of the neuronal cells in diabetes." (PMID 35935990, 2022). "Fan Xiaoming studied the role of interleukin-10 in reducing renal injury after myocardial infarction in diabetes." (PMID 36712879, 2022). "Pancreatic expression of IL-10 can up-regulate the expression of intercellular adhesion molecule 1 (ICAM-1) on vascular endothelium and promotes diabetes development, but systemic IL-10 is dispensable for autoimmune diabetes." (PMID 34394099, 2021).
diabetes (continued). "Most importantly, Il-10 deficiency changed the function of CD4+ T cells as BDC2.5+Il-10-/- CD4+ T cells were more pathogenic and induced rapid diabetes onset in NOD.scid mice compared with those CD4+ T cells from BDC2.5+Il-10+/+ NOD mice." (PMID 34394099, 2021). "Combined administration of L. lactis MG1363 FnBPA+ (pValac::dts::IL-4) and L. lactis MG1363 FnBPA+ (pValac::IL-10) resulted in protection against diabetes in NOD mice." (PMID 33604389, 2021). "Signaling through TLR9 changes the frequency and function of IL-10 producing B cells in NOD mice; TLR9 deficiency specifically in B cells increased IL-10 producing cells and protected against diabetes." (PMID 34616408, 2021). "Similar to the adoptive transfer with total splenocytes, CD4+ T cells from BDC2.5+Il-10-/- NOD mice induced rapid onset of diabetes compared to their counterparts from BDC2.5+Il-10+/+ NOD mice." (PMID 34394099, 2021). "The role of combination therapy (PPI+TFGβ+IL10) with anti-CD3 for the prevention of diabetes in NOD mice, vaccinated with Salmonella ΔhtrAΔ/purD mutant, was reported." (PMID 34108968, 2021). "We showed that two doses of Salmonella-based combined therapy (PPI+TGFβ+IL10) with a sub-therapeutic dose of anti-CD3 mAb prevented diabetes in NOD mice." (PMID 34108968, 2021). "As for the Th2 cytokines, the IL-6 and IL-10 levels in patients with diabetes in week 1–3, and IL-8 in week 1–3 were significantly higher than those in patients without diabetes." (PMID 33776910, 2021). "In this study, we developed a markedly accelerated model of type 1 diabetes by introducing an Il-10 deficiency to BDC2.5+ NOD mice, whereas Il-10 sufficient BDC2.5+ NOD mice develop a very low incidence and delayed spontaneous diabetes." (PMID 34394099, 2021). "The prevention of the incidence of diabetes is increased to 80% after vaccination with ΔmsbB and PI+TGFβ+IL10+anti-CD3." (PMID 34108968, 2021). "Supporting the in vitro data, splenocytes from diabetic BDC2.5+Il-10-/- NOD mice showed more potent diabetogenicity by inducing a higher incidence of diabetes in the recipients, compared with the splenocytes from BDC2.5+Il-10+/+ NOD mice." (PMID 34394099, 2021). "Approaches favoring Th2 activity and administration of cytokines that downregulate Th1 activities, such as IL-4 and IL-10, have shown success in suppress insulitis and prevent diabetes." (PMID 33604389, 2021). "Analysis showed that diabetes incidence increased in the saline-NOD group from week 15 onwards, while mice in the F-IL-4/IL-10-NOD group remained protected against diabetes during the entire experimental period." (PMID 33604389, 2021). "Despite all groups that received STZ injections became diabetic, it was noteworthy that the F-IL-4/IL-10-STZ group presented the highest number of mice protected against diabetes incidence." (PMID 33604389, 2021). "In diabetes, the beneficial role of IL-10 on pancreatic β-cell functions and skeletal muscle was demonstrated in diabetes type I." (PMID 32824505, 2020). "From in vivo studies, osthole (20 mg/kg per day for 14 days) reduced the up-regulation of the P2X4 receptor, and downregulated the IL-1β, TNF-α, brain-derived neurotrophic factor, and p-p38MAPK and upregulated IL-10 in diabetes mellitus." (PMID 32028721, 2020). "Accumulating evidence suggests roles for NOD-like receptor family pyrin domain containing 3 (NLRP3) in mediating inflammation and interleukin-10 (IL-10) in mediating anti-inflammatory effects in diabetes and cardiovascular diseases." (PMID 32273846, 2020). "Other corroborating evidences are the increased inflammatory markers (NF-κB, TNFα, IL-6, and IL-10) reported in cortical tissues of murine diabetes models, HK2 cell cultures under high glucose environment (NF-κB), and cortical portions of T2D patients (NF-κB)." (PMID 32377524, 2020).
diabetes (continued). "TNF-α and IL-1β were increased in the liver of GDM offspring, whereas IL-10, an anti-inflammatory cytokine, was decreased in GDM offspring, indicating an increased risk of developing diabetes." (PMID 31340612, 2019). "In the covariate models, higher age was associated with increased TNF-α and IL-6, and presence of diabetes with higher concentrations of TNF-α, IL-6, and IL-10." (PMID 31755034, 2019). "When rUTI patients with diabetes, taking oestrogen supplements, or a history of vaginal prolapse, or prostate enlargement (n = 19), were excluded from the analyses the IL-10 data relating to E. coli loads ≥105 CFU/ml remained significant (P = 0.00002)." (PMID 31338112, 2019). "Our previous studies have shown that IL10 delays the onset of diabetes in NOD mice treated with Salmonella-based vaccine." (PMID 30863412, 2019). "we now find that IL10 is essential for stabilization of blood glucose in NOD mice after reversal of diabetes." (PMID 30863412, 2019). "Previous studies suggested that the low expression of this cytokine in the pancreas mediates the occurrence of diabetes and decreased IL-10 levels in serum of newly diagnosed children with type 1 diabetes has been observed." (PMID 30061883, 2018). "Diabetes also raised the anti-inflammatory cytokine IL-10 levels, which was commonly induced in response to inflammation." (PMID 30319431, 2018). "Although previous reports have suggested a relationship between IL-10 and diabetes, as well as its complications such as DM nephropathy, only a limited amount of data specifying the association between IL-10 methylation and GDM development has been published." (PMID 29988451, 2018). "Compared with NC, the levels of serum inflammation indexes like CRP, IL6, IL8, TNF-α, and CCL2 were significantly increased (p < 0.05), while IL10 levels were significantly decreased (p < 0.05) in diabetes groups (MC, WP and SCCOPs-treated groups)." (PMID 29316680, 2018). "A statistically significant difference between controls and subjects with diabetes at baseline was observed in aqueous humor levels of the following cytokines: IL-10, IL-12p70, IL-12p40, IL-15, EGF, FGF-2, VEGF, MIP-1β, MCP-3 and MDC (p < 0.05; p < 0.001)." (PMID 30410092, 2018). "Added to these, a direct relationship has been established between increased cytokines, such as tumour necrosis factor-α (TNF-α), interleukin 6 (IL-6) and interleukin 10 (IL-10) and excessive hyperglycaemia in both types 1 and 2 diabetes." (PMID 28974040, 2017). "In individuals with periodontitis and type 2 diabetes, serum concentrations of TNF-α and IL-10 were higher in patients with diabetes and IL-10 levels were strongly correlated with the severity of periodontal disease." (PMID 28906456, 2017). "As observed in our results, β-glucan treatment decreased both TNF-α blood levels in animals with periodontal disease and diabetes and IL-10 levels in animals with periodontal disease." (PMID 28906456, 2017). "Our group found that through NF-κB inhibition, P. hepiali suppressed the release of proinflammatory cytokines, including tumor necrosis factor alpha, IL-2, IL-6 and IL-10, in a rat model of diabetes induced by a high-fat diet and STZ." (PMID 28662169, 2017). "Consistent with the quantitative assay, the protein expression of IL-10 was suppressed in diabetes and was enhanced in diabetic animals treated with Ex4." (PMID 29095895, 2017). "On the other hand, the tissue content of IL-10 was reduced in diabetes, but was restored in the Ex4 treated rats." (PMID 29095895, 2017). "IL-10, as a pivotal anti-inflammatory cytokine, is usuallydownregulated during the development of diabetes." (PMID 27074164, 2016). "Significant main effect of diabetes was observed in IL10 (P = 0.001) and its protein abundance significantly decreased by 78% (P = 0.001) in the muscle of db/dbCON mice relative to that of db/+CON mice." (PMID 27512375, 2016).
diabetes (continued). "There is a clear association between the inflammatory biomarkers used to calculate the DII score (CRP, IL-1β, IL-6, TNF-α, IL-4, and IL-10) and cardio-metabolic diseases such as obesity, diabetes, or CVD." (PMID 27527152, 2016). "Diabetes resulted in significantly reduced levels of the anti-inflammatory cytokine IL-10 in whole-retina homogenates, which were completely restored in mice treated with A-285222." (PMID 25918731, 2015). "Increased inflammation due to induction of pro-inflammatory cytokine such as tumor necrosis factor-alpha (TNF-α) and attenuation of anti-inflammatory cytokine such as interleukin 10 (IL-10) contributes to cardiac dysfunction in obese and diabetics." (PMID 25954207, 2015). "Several diabetes-related or inflammation-related genes are included in the TG-associated pathways, such as SMAD3, TGFB1, CDKN2B, and IL10." (PMID 26308950, 2015). "In the STZ-mouse model of diabetes that we used here, 2 weeks of diabetes resulted in decreased levels of IL-10." (PMID 25918731, 2015). "It is possible that the timing and location of IL-10 production and the cell types exposed to IL-10 are crucial factors in diabetes development, as systemic administration of IL-10 prevents the onset of diabetes." (PMID 23671851, 2013). "Several studies have been conducted in recent years to evaluate the risk of type 2 diabetes mellitus (T2DM) and polymorphisms of interleukin (IL)-10." (PMID 23805237, 2013). "Recently we demonstrated that a combination of rVV-CTB::GAD with the rVV-IL10 virus expressing the antiinflammatory cytokine IL-10 was effective in preventing diabetes onset in NOD mice." (PMID 24319466, 2013). "This study describes novel observations regarding the differences in acute inflammatory responses of IL-6, IL-10, and IL-18 for severely obese patients with type 2 diabetes mellitus (DM) from the responses of lean patients." (PMID 24555158, 2013). "While IL-10 can inhibit diabetes under certain circumstances, transgenic expression of IL-10 in the pancreas can actually exacerbate diabetes." (PMID 23849743, 2013). "That IL-10 present in the lumen can exert biological activity is shown in a mouse model of autoimmune encephalomyelitis and diabetes where orally administered IL-10 effectively enhanced tolerance induction." (PMID 21464967, 2011). "A recent study has also shown that injection of GM-CSF into prediabetic NOD mice prevents diabetes development by inducing IL-10-producing tolerogenic DCs that sustain the suppressive function of CD4+CD25+ regulatory T cells." (PMID 21716731, 2011). "The role that IL-10 plays in diabetes development in NOD mice is complex, since IL-10 appears to be involved in diabetes pathogenesis as well as diabetes prevention." (PMID 21716731, 2011). "LTA-treated DCs produced much more IL-12 than IL-10 and accelerated diabetes development when transferred into NOD mice." (PMID 21716731, 2011). "There was a decrease in protection in mice treated with the anti-IL-10R antibodies when compared to mice treated with isotype control, confirming a role for IL-10 in diabetes protection mediated by injection of Lactobacilli-treated DCs." (PMID 21716731, 2011). "The suppressive role of IL-10 in Th1 and Th2 cell-mediated immunity will provide a further way by which iNKT cells can modulate adaptive immunity and iNKT cell-derived IL-10 is thought to suppress tumor immunity and protect against diabetes." (PMID 22174854, 2011). "Previous reports in the NOD model of diabetes have shown that the administration of the probiotic formulation VSL3 decreased the incidence of T1D through IL10 immunomodulation and induction of pro-inflammatory cytokine IFNγ." (PMID 20463897, 2010). "In fact, IL-10 attenuates the increases in vascular superoxide and endothelial dysfunction during diabetes and atherosclerosis." (PMID 20462420, 2010). "Pancreas specific IL-10 transgenic mice have been shown to develop spontaneous inflammation and diabetes." (PMID 19771172, 2009).